HLA-B (major histocompatibility complex, class I, B)
Diseases named in the same sentence as HLA-B in open-access papers (continued):
Sharing a sentence is not in itself a finding about the gene and the disease.
infection (continued). "HLA-B*44:03 restricted epitopes, M27–15, NS1195–203, PB239–49 and HA445–453, showed similar slower presentation kinetics with detectable presentation at 2 h and 50% presentation at approximately 6 h after infection." (PMID 34198851, 2021). "In summary, HLA-B*57-negative patients displayed altered patterns of CD8 T-cell differentiation in comparison to HIV-negative subjects within the first year of infection, patterns which were not apparent in HLA-B*57-positive patients." (PMID 32350076, 2020). "Despite the patient displayed favorable prognostic indicators—symptomatic course of infection, IL28B/IFNL4 CC genotype and HLA-B*27 expression—he did not succeed in clearing the virus and developed persistent low-level infection with HCV." (PMID 32183384, 2020). "Herein, we demonstrate that primary CD8+ T cells from HLA-B*57/5801 elite suppressors were able to efficiently eliminate resting and activated primary CD4+ T cells shortly after viral entry and prior to productive infection." (PMID 23816179, 2013). "In line with this, our previous results show that biological viral variants from LTNPs obtained early and late in infection do not differ in their replication kinetics, whereas in HLA-B*57/58:01 progressors viral fitness increased over the course of infection." (PMID 24339913, 2013). "Subsequently, after infection the cells were cultured for different incubation times (0–24 h) to allow endogenous antigen processing, then added to peptide-specific CTL lines restricted by HLA-B*27 or HLA-A*02, respectively." (PMID 23209413, 2012). "Importantly, the induction of IFN-γ in HLA-B*27-restricted CD8+ T cells was higher at two and four hours after infection compared to HLA-A*02-restricted CD8+ T cells, even despite the lower avidity of the HLA-B*27-restricted CD8+ T-cell responses." (PMID 23209413, 2012). "We therefore were interested in the relation of memory T-cell responses and outcome of their ANDV infection in HLA-B*35-positive and negative patients." (PMID 20174562, 2010). "Conversely, immunization of HLA-B*0702 mice with the DENV1-NS poly-epitope, which contains eight epitopes from DENV1, of which six have similar sequences with DENV2 peptides, induces a significant protection against both DENV1 and DENV2 infection (and this study)." (PMID 39418312, 2024). "There are no reports of HLA-B*15:02-restricted epitopes in HIV-1 subtype A/E infection." (PMID 36154612, 2022). "Among non-HLA-B*57-restricted responses, the frequency of GrzA-expressing cells decreased (estimated unit change per additional wpi, −0.058; P = 0.010), while the respective counterparts showed no significant change with duration of infection." (PMID 32350076, 2020). "Moreover, class I HLA-B*7 is correlated with accelerated disease progression in B-clade infection, but not in C-clade infection." (PMID 30534128, 2018). "While very strong associations have been reported from a number of different cohorts between non-progressive infection/HIV-1 control and the HLA-B alleles B57 and B27, not all individuals with this genotype are atypical progressors, and conversely, not all atypical progressors possess this genotype." (PMID 23459797, 2013). "Examination of Gag sequences from acutely infected HLA-B*57/5801 negative women has revealed two polymorphisms, A146X and T242N, that are associated with lower viral loads and higher CD4+ counts in these woman up to a year post infection." (PMID 18369479, 2008). "When measured individually, HLA-B, -C, and -E were significantly upregulated by FM-MA infection, whereas PR8 and CA/07 infections elicited modest increases in HLA-B, which did not achieve statistical significance." (PMID 32321802, 2020). "Whereas less than two-fold reduction for HLA-B surface expression was observed, HLA-A*02:01 was reduced 3-fold in the presence of US11 as compared to infection with the virus lacking US11." (PMID 31527904, 2019).
infection (continued). "Moreover, the association of HLA-B*2705 with good HIV-1 control is thought to be largely attributable to early targeting of a highly conserved Gag epitope by the most immunodominant HLA-B*2705-restricted T cell response, escape from which is typically not observed until many years post-infection." (PMID 25569444, 2015). "In summary, we established HLA-B*51:01 transgenic humanized mice and demonstrated the elicitation of human effector CD8+ T cells, but no GVH reaction, in the mice after infection with HIV-1." (PMID 22880104, 2012). "However, one remarkable finding was the almost total absence of HLA-B and/or -C expression in some individuals, indicating that some individuals may have a reduced MHC class I repertoire, which may affect their sensitivity to infection by intracellular parasites." (PMID 35163105, 2022).
cancer (99 papers, 2003 to 2025). A tumor composed of atypical neoplastic, often pleomorphic cells that invade other tissues. "Specifically, the HLA-B allele results in 203 cancer patients in Taiwan showed that the highest frequencies of HLA-B alleles were for HLA-B*46 (18.0%), -B*58 (12%), -B*15 (11.2%), and -B*38 (4.6%)." (PMID 36649009, 2023). "Specifically, loss-of-function mutations in HLA-A and HLA-B, as well as multiple genes from other immune escape pathways, displayed higher-than-expected frequencies across several cancer types." (PMID 37165135, 2023). "Although in this regard no data was found for HPV 39, it is indicated that the E-G350 variant of HPV 16 had 4–fivefold higher risk for cancer development among Swedish women with HLA-B*44, HLA-B*51, or HLA-B*57 alleles." (PMID 34294082, 2021). "We collected publicly available HLA-peptides MS data from 16 mono-allelic HLA-A and HLA-B cell lines genetically engineered to express a single HLA allele and from B lymphocytes or cancer cell lines expressing multiple HLA complex alleles." (PMID 34113354, 2021). "For example, next-generation sequencing is offered to veterans diagnosed with cancer, and pharmacogenetic testing of the HLA-B*57:01 allele prior to prescribing abacavir is already standard of care." (PMID 31173123, 2019). "Another study has shown that donors and recipients of HLA matching locus and the occurrence of cancer after transplantation, HLA-B, and two sites in a mismatch risk was 1.4 (0.5–4.1) and 5.1 (1.4–19.0)." (PMID 25667935, 2015). "A statistical significant difference, where cancer-associated peptides contained more predicted epitopes was, on the other hand, only observed for one supertype representative, namely HLA-B*27∶05." (PMID 23049726, 2012). "Specifically, further research is needed to ascertain whether the alterations in HLA-E, B2M, and HLA-B, as indicated in our findings, are indeed linked to cancer immune evasion through the loss of MHC Class I antigen presentation." (PMID 38256174, 2024). "We also observed lower expression of MHC-I genes on EMM cells (HLA-B, HLA-C), which may be associated with reduced efficacy of cancer immunotherapies due to decreased recognition of malignant cells by effector T cells." (PMID 38493239, 2024). "Since heterozygosity at classical HLA-I genes or high HED levels of HLA-B alleles had been found to be associated with improved survival in cancer patients treated with ICIs, we assumed that individuals who are heterozygous for HLA or with high HED levels also have a higher incidence of irAEs." (PMID 36177028, 2022). "On these bases, the proinflammatory and ERS induced by the HLA-B*35 allele as well as the Th2-promoting ability of DRB1*11 might explain the increased rate of IRPs in cancer patients receiving PD-1/PD-L1 immune checkpoint inhibitors." (PMID 32854442, 2020). "Similar studies need to be conducted in cancer patients to determine whether individuals with HLA-B*27 and HLA-B*57 alleles are more protective than the others." (PMID 28769934, 2017). "Next, the role of the HLA-B −21M/T genotype in the recurrence and the progression of the disease and the survival of cancer patients was evaluated." (PMID 39857739, 2025). "The transition areas (II) that encompass both cancer cells and immune cells as defined in the original study exhibit high expression of FTL, CTSB, and HLA-associated genes (e.g., HLA-A, HLA-B, HLA-C), indicating immune infiltration in the TME." (PMID 40033360, 2025). "Conversely, major histocompatibility complex (MHC) class I molecules (HLA-A, HLA-B, HLA-C) were progressively downregulated, a common immune evasive strategy by cancer cells to thwart immune detection and clearance." (PMID 40858992, 2025). "This confirmed that MHC-I heavy chain transcripts (HLA-A, HLA-B, and HLA-C) are consistently upregulated in response to BQ across diverse cancer types." (PMID 37066260, 2024).
cancer (continued). "(F) RT-qPCR quantification of HLA-A, HLA-B, and HLA-C mRNA levels in cancer cell lines after 24 hr BQ treatment." (PMID 38973593, 2024). "Withinthe same cancer type, the homozygosity rate is consistently the highestfor the HLA-A gene (mean = 18.9% across all nine cancers) and thelowest for the HLA-B gene (mean = 7.0%) with the biggest differencearound 15% in LUAD and HNSCC tumors." (PMID 37857377, 2023). "We found that cancer cells with higher levels of CNV displayed lower levels of MHC-I genes (HLA-A, HLA-B and HLA-E) and the B2M gene, suggesting that these cancer cells were less immunogenic." (PMID 36596773, 2023). "We investigate new protein–protein interactions for IFITM1/3 in the context of cancer that would shed some light on how IFITM1/3 attenuate the expression of targeted proteins such as HLA-B." (PMID 36008984, 2022). "We thus compared the mutational frequencies of cancer driver genes between the high- and low- HLA-B HED subgroups in patients with HLA-B heterozygosity (n = 71)." (PMID 34732240, 2021). "Supporting a key role for epigenetic regulation of MHC-I expression in cancer cells, all the top candidate genes identified from cells with reactivated MHC-I detected with either an HLA-B-specific or a pan-HLA-A/B/C antibody encoded epigenetic regulators." (PMID 31564637, 2019). "Only one supertype representative (HLA-B*40∶01, locally permutated) had significantly more predicted epitopes in the permutated cancer sequences than in the permutated normal sequences." (PMID 23049726, 2012). "Our study reveals a significantly increased frequency of HLA-B*1501 in cancer patients in comparison to healthy controls (OR = 3.714; CI95%, 1.187–11.619, p = 0.031) but not in other HLA-B alleles." (PMID 19196481, 2009). "A central question is whether the cancer type specific hierarchy of HLA class I gene (HLA-A, HLA-B, and HLA-C) expression observed in the CCMA cohort is preserved in primary tumors." (PMID 41312385, 2025). "In addition, we observed decreased expression of MHC-I molecules HLA-B and HLA-C in EMM cells, a phenomenon previously associated with a worse response to immunotherapy in other types of cancer." (PMID 38493239, 2024). "The Major Histocompatibility Complex Class I (MHC-I), including isoforms such as HLA-B, is fundamental in presenting peptide epitopes on the surface of cancer cells, facilitating their recognition by CD8 T cells, and mobilizing their cytotoxic response against malignancies." (PMID 39081317, 2024). "Finally, gene and cancer type-specific analysis showed that HLA-A and HLA-B were deemed as drivers across several cancer types, including metastatic colorectal, NSCLC and DLBCL as well as the pan-cancer cohorts." (PMID 37165135, 2023). "Other dMMR/MSI‐associated immune escape mutations that varied in frequency between cancer types included RPL22, which was enriched in EC, and the antigen processing and presentation pathway components B2M, NLRC5, TAP2, and HLA‐B, which were more commonly disrupted in CRC." (PMID 35262923, 2022). "Although we focused on the role of IFITM1/3 in regulating HLA-B, there may be other cancer- and virus-originated proteins for which expression may be mediated by IFITM1/3." (PMID 36008984, 2022). "We found that HLA-A and HLA-B showed higher HED than HLA-C in cancer patients." (PMID 36177028, 2022). "HLA-I (MHC-I), of great importance, consists of a highly polymorphic α-heavy chain and a β2-microglobulin (β2M) light chain, encoded by the HLA-A, HLA-B, or HLA-C genes, delivers peptides to CD8+ T cells, and is essential for immune surveillance and cancer immunotherapy." (PMID 34805135, 2021).
cancer (continued). "The availability of TCRs directed against 7-16V/HLA-A*03:01 (TCRA3V), 7-16V/HLA-A*11:01 (TCRA11V), and 10-19R/HLA-B*07:02 (TCRB7R) permitted their use as sensitive probes demonstrating the presence of these p-HLA complexes on the cell surface of various cancer cell lines from multiple histologies." (PMID 34272369, 2021). "If so, HLA-B,C antigens represent a new target to affect cancer cell metabolism and motility." (PMID 31454998, 2019). "Similarly, the expression of HLA-B in cancer cells was helpful in activating the activation and proliferation of CD8+T cells." (PMID 31905767, 2019). "Indeed, the expression of MHC class I molecules (HLA-A, HLA-B, and HLA-C) on cancer cells allows their detection and destruction by T cell lymphocytes." (PMID 29930758, 2018). "However, there should be many useful HLA-B-restricted epitopes, including already known cancer antigens." (PMID 27050553, 2016). "If HLA-B-restricted CTLs could also be stimulated, the efficacy of anti-cancer vaccination therapies would be improved substantially." (PMID 27050553, 2016). "Indeed, it has been suggested that women with three distinct HLA class I alleles, namely HLA-B*44, HLA-B*51, or HLA-B*57 who were infected with the HPV16 E6 variant L83V had an approximately four to five fold increased risk for cancer compared with controls." (PMID 23953248, 2013). "For non-permutated sequences, seven out of the twelve supertype representatives (HLA-A*01∶01, HLA-A*02∶01, HLA-A*03∶01, HLA-A*24∶02, HLA-A*26∶01, HLA-B*15∶01 and HLA-B*58∶01) had a significant lower fraction of predicted epitopes in sequences assigned to cancer pathology." (PMID 23049726, 2012). "Moreover, CD247, CD3G, HLA‐B, HLA‐C, and HLA‐F took part in various pathways, including Th1 and Th2 cell differentiation, PD‐L1 expression and PD‐1 checkpoint pathway in cancer, Th17 cell differentiation, antigen processing presentation, allograft rejection, and cell adhesion molecular." (PMID 35037412, 2022). "To achieve a comprehensive and objective evaluation of MHC-I expression in cancers, we developed a MHC-I signature score based on GSVA of eight MHC-I family genes, including HLA-A, HLA-B, HLA-C, HLA-D, HLA-E, HLA-F, HLA-H, and B2M." (PMID 39408874, 2024). "Of these genes, TAP2, B2M, IRF1, TAP1, HLA-A, HLA-B and HLA-C were formally and independently classed as CRC drivers, with strongest signals in MSI cancers, but also discovered in MSS cancers (for example, HLA-A and B2M)." (PMID 39112709, 2024). "In zabadinostat-treated HCT116 cancer cells, treatment with the CIITA siRNA reduced the level of MHC class I HLA-A and -C but had less effect on HLA-B and -E." (PMID 36702861, 2023). "We additionally identified as positive biomarkers several interactions between MHC-I genes and the corresponding receptors (HLA-B_HLA-E → KLRD1 and HLA-E → KLRC1 in 17 and 14 cancer types, respectively)." (PMID 34430923, 2021). "NK cells' cytotoxic activity is mediated by the level of expression of MHC molecules—HLA-A, HLA-B, and HLA-C—and KIR receptors on cancer cells." (PMID 30425720, 2018). "We used the PLK1 inhibitor (BI2536) to treat cancer cell lines and compared expression levels of MHC class I (HLA-A, HLA-B, HLA-C, B2M, and TAP1 genes and their protein products) between the pre- and post- treated cell lines." (PMID 30631355, 2018). "Inspection of the analyzed gene set revealed that, among the ten most specific immune response cancer genes, five were bound to or an integral part of the plasma membrane (CD70, HLA-B, TNF, TNFRSF14, and CD79B)." (PMID 26856619, 2016). "Multivariate analysis revealed that expression of HLAA, HLAB, and HLAC were all significantly less in MSI-H than MSS cancers (p = 0.027, p = 0.017, and p = 0.018, respectively for HLA-A, B and C), consistent with previous observations." (PMID 25949894, 2015).
cancer (continued). "Furthermore, the expression of GPX4 was closely associated with MHC molecules, immune activation genes, and immunosuppressive genes such as HLA-A, HLA-B, CD160, TNFRSF18, TNFRSF4 and CD276 in most cancer types." (PMID 41142608, 2025). "HLA-B, a molecule in the MHC class I family, plays a critical role in the cell-mediated immune response by presenting intracellular proteins or neoantigens produced by cancer cells to effector CD8+ T cells, thereby initiating an immune response." (PMID 39954675, 2025). "Multiple cancer types in TCGA shared common ISGS genes (CX3CR1, IL7, and HLA-B)." (PMID 39796714, 2024). "Next, pan-cancer and gene-specific dN:dS ratios showed that HLA-A and HLA-B, but not HLC-C, are positively selected and are mostly enriched in truncating variants but not in missense mutations." (PMID 37165135, 2023). "There are classical forms, HLA-A, HLA-B, and HLA-C, and non-classical forms, HLA-G, HLA-E, HLA-F, and HLA-H, of this protein; both have been identified in cancer with diverse roles." (PMID 34359613, 2021). "When cancer cells (i.e., A549, HCC827, CNE2 and HONE1 cells) were transiently transfected with miR-19a or miR-19b-1 mimics, qRT-PCR data revealed a general downward trend in the expression profile of the MHC Class I genes (such as HLA-B, HLA-F, HLA-G)." (PMID 32308549, 2020). "Fourth, HLA-B is also down-regulated in PBC, similar to several types of cancer." (PMID 24734033, 2014). "Interestingly, ANGPTL2 mRNA levels show a significant positive correlation with those of JARID2 mRNA, and levels of both are negatively correlated with those of HLA‐B and HLA‐C mRNAs in cancer lines derived from metastatic rather than primary lesions." (PMID 37452654, 2023). "This study demonstrated that miR-19a or miR-19b-1 overexpression in cancer cells led to a general downward trend in the expression profile of MHC Class I molecules (such as HLA-B, HLA-E, HLA-F, HLA-G or HLA-J), which has never been reported in other physiological and pathological processes." (PMID 32308549, 2020).
infectious disease (13 papers, 2013 to 2025). A disorder directly resulting from the presence and activity of a microbial, viral, or parasitic agent in humans. "Many corresponding positions in human HLA-B have associations with autoimmune or infectious diseases, biomarkers, or TCR phenotypes." (PMID 40937493, 2025). "The high variability in the HLA-B gene must be studied in light of the role of their alleles in infectious diseases, so common in developing countries." (PMID 37169817, 2023). "Various studies have analyzed the association of HLA-B and HLA-C with other infectious diseases." (PMID 38674456, 2024). "HLA-B displays the strongest selective signal and associations with infectious diseases." (PMID 35669157, 2022). "The major histocompatibility complex gene class I, B (HLA-B) plays a role in the immune response to viruses and infectious diseases." (PMID 37606455, 2023). "An additional feature is the high frequency of HLA-B*46:01, which may have arisen due to selection pressure from infectious disease." (PMID 33995358, 2021). "Some genes were common across different fields (e.g., HLA-B in neurology and infectious disease)." (PMID 32708157, 2020). "Thus, HLA-B*57 can exert ambiguous functions in infectious diseases depending on the precise environmental circumstances." (PMID 26241854, 2015).